ALK (ALK receptor tyrosine kinase)
Diseases named in the same sentence as ALK in open-access papers (continued):
Sharing a sentence is not in itself a finding about the gene and the disease.
tumor (continued). "Consistently, our ALK positive cases had a larger tumor size (median 5 cm vs. 3 cm) than the negative ones (0.037)." (PMID 32876329, 2021). "Moreover, neurolenin B specifically decreased pro-carcinogenic NPM/ALK expression in ALK+ ALCL cells, and attenuated tumor intra/extravasation into the lymphatics." (PMID 34959370, 2021). "Finally, we assessed the levels of survivin (the downstream target oncogene in the ALK and STAT3 pathways) in tumor tissues." (PMID 33758275, 2021). "Therefore, the use of CT features for patients can allow analyses of tumours and more accurately predict patient populations who will benefit from EGFR-TKIs or ALK crizotinib treatment." (PMID 33707479, 2021). "The mRNA expression levels of various RTK genes, including VEGFR-1, VEGFR-2, PDGFR-α, PDGFR-β, anaplastic lymphoma kinase (ALK), epidermal growth factor receptor (EGFR), ErbB2, and B-RAF were compared between the tumor and adjacent normal tissues collected from the patient." (PMID 33764261, 2021). "In this study, we investigated whether ALK receptor is active in MCC tumor samples and MCC cell lines, and whether ALK would be a prospective treatment target in MCC." (PMID 34029351, 2021). "For instance, miR-155, which was first identified as abnormally expressed in CTCLs, can be used as an oncogenic driver to promote tumor growth in both MF and anaplastic lymphoma kinase (ALK)-negative anaplastic large-cell lymphoma (ALCL)." (PMID 34966672, 2021). "In the special case of ALK+ NSCLC, next-line use of ALK inhibitors is “open”, i.e. not dependent on the molecular results of a tumor rebiopsy at the time of disease progression." (PMID 33959513, 2021). "Analysis of MCC tumor samples revealed that the presence of p-ALK correlated to MCPyV positivity, younger age, nonexistence of metastases at diagnosis and ultimately to better MCC-specific survival." (PMID 34029351, 2021). "However, for a definitive diagnosis, an ALK-rearrangement by FISH is necessary, typically showing an ALK split signal in the majority of tumor cells." (PMID 31936678, 2020). "ALK-A and -CNG have been studied in different tumor types, not always related to ALK protein overexpression or increased downstream signaling." (PMID 32664698, 2020). "ALK tissue FISH analyses were performed on 42 tumor samples, but not on the second samples of two patients (cases #18 and #19)." (PMID 32674491, 2020). "Most samples with the pure non-canonical ALK fusions had positive IHC, indicating that most of the identified non-canonical ALK fusions were likely to express the fusion products in the tumor." (PMID 33363027, 2020). "Clinically, ALCL with ALK gene fusion displays extremely aggressive tumor phenotypes but paradoxically, these patients have noticeably better prognosis than those without ALK fusion (with 71% vs. 15% of patients surviving over 10 years)." (PMID 32059449, 2020). "Nineteen (4.9%) of these patients had tumor samples that exhibited inconsistent intersample ALK FISH results (positive to negative or vice versa)." (PMID 32674491, 2020). "If tumor cells carry both EGFR and ALK alterations, a combination of both TKIs may be a potentially reasonable choice." (PMID 33363040, 2020). "Only 1 patient’s tumour with GBC was successfully analysed, in whom an ALK fusion was identified." (PMID 32899345, 2020). "The tumor cells were robustly and diffusely positive for Trk, S100-protein, CD34, and nestin, but negative for CD56, SMA, desmin, myogenin, STAT6, EMA, CK, CD1a, CD21, CD35, CD43, WT-1(c-terminal), MelanA, HMB45, BRAF, and ALK." (PMID 32957984, 2020). "Eight tumor samples from five patients in this cohort were tested by RNA-seq, and five (62.5%) were positive for EML4-ALK fusion; all of these samples were collected before ALK TKI administration." (PMID 32674491, 2020).
tumor (continued). "By immunohistochemistry, tumor cells demonstrated strong nuclear cyclin D1 expression and multifocal smooth muscle actin staining but were negative for MUC4, ERG, CD34, S-100 protein, desmin, STAT6, CD45, MDM2, CDK4, ALK, and ROS1." (PMID 32461620, 2020). "In this study, we present an EGFR- and ALK-negative advanced NSCLC case for which we conducted comprehensive tumor genomic profiling to identify potentially actionable alterations." (PMID 32190395, 2020). "Clinicopathological characteristics, driven genes’ status (EGFR, ALK, and ROS1), adjuvant chemotherapy strategy for 94 surgical resected LCNECs were extracted from digital database, tumor relapse or progression, and survival were analyzed with clinical profiles." (PMID 33335851, 2020). "Furthermore, a new anaplastic lymphoma kinase (ALK) transcript, ALKATI, was recently encountered in STS patients, where its expression correlated with tumor grade (p = 0.010) and tumor size (p = 0.036), and with worse PFS (p < 0.05)." (PMID 32532153, 2020). "Additional genetic alterations can co-exist with a primary targetable oncogenic “driver” alteration (e.g., oncogenic EGFR, ALK, KRAS) and may help promote tumor progression and limit therapy response." (PMID 32822576, 2020). "The tumor cells were between 5% and 90% in FFPE sections of our ALK‐positive cohort." (PMID 32543087, 2020). "A immunohistochemical analysis showed that PD-L1 expression was higher in NSCLC tumor specimens positive for ALK rearrangement than in those negative for ALK translocation." (PMID 33324391, 2020). "The Vysis LSI ALK break-apart probes showed clear ALK translocations in the ALK-positive tumor slides and the non-ALK-translocated tumor tissue showed no signal separation." (PMID 32549278, 2020). "Nevertheless, their findings suggest that EGFR+/ALK+ NSCLC patients could also benefit from ICI, especially EGFR+ patients with ≥25% PD-L1-expressing tumor cells." (PMID 32011450, 2020). "Since oncogenic driver alterations may modulate immune response in tumor microenvironment that may influence prognosis in LUAD, the effects of EGFR, ALK, ROS1, and BRAF alterations on tumor microenvironment remain unclear." (PMID 33585210, 2020). "Recently larotrectinib, a pan-TRK inhibitor, and entrectinib, a pan-TRK, ALK, and ROS1 tyrosine kinase inhibitor, were the first tumor-agnostic-targeted therapies developed and approved in oncology for the treatment of pediatric and adult tumors that have an NTRK gene fusion." (PMID 32087721, 2020). "The tumor cells in our case were positive for both ALK and CD117, and it was thus difficult to determine whether the tumor was an IMT or a GIST." (PMID 32005261, 2020). "Immunophenotypically, the tumor was positive for vimentin, epithelial membrane antigen (EMA) and negative for CK-pan, CAM5.2, CD31, CD34, smooth muscle actin (SMA), desmin, anaplastic lymphoma kinase (ALK), calponin, TTF-1 and S-100 protein." (PMID 32039736, 2020). "Among patients with a tumor proportion score of ≥50% for PD-L1 and lacking sensitizing EGFR or ALK mutations, pembrolizumab has replaced cytotoxic chemotherapy as the first-line treatment of choice." (PMID 33101670, 2020). "The favourable response achieved with radical radiotherapy alone in this unusual case of indolent oncogenic NSCLC reinforces the applicability of radiotherapy in locally advanced ALK-rearranged tumours, in cases not behaving aggressively." (PMID 32762670, 2020). "Recent findings have indicated strong and durable activity of crizotinib in ALK positive IMTs regardless of the tumor location." (PMID 32430041, 2020). "A negative correlation was identified between the level of ALK autoantibodies and tumor relapse (i.e., the higher the level of ALK auto-antibodies, the lower the risk of disease relapse)." (PMID 32059449, 2020).
tumor (continued). "In the current study, we presented an exceptional case of a young patient with ALK rearrangement-positive LCNEC treated with ALK-TKI, who exhibited concomitant regression of both primary tumor and multiple metastatic lesions after the treatment despite the heterogeneous TIME." (PMID 33352665, 2020). "The presence of gene rearrangements in ALK, ROS1 or NTRK has been associated with worse survival (15.6 versus 33.7 months for patients with [n = 27] or without [n = 319] tumour gene fusions, respectively)." (PMID 32418154, 2020). "However, some actionable targets can be present in other genes (notably MET, RET, NTRK, and HER2), allowing inclusion into clinical trials of patients with EGFR, ALK, ROS1, and BRAF wild-type tumors with less than 50% PD-L1-positive tumor cells." (PMID 32294880, 2020). "The tumour cells in ALK-negative ALCL demonstrate similar heterogeneity but the small cell pattern is not usually seen." (PMID 31871676, 2020). "The development of molecularly targeted therapies, as well as ICIs, has improved outcomes in the metastatic setting for NSCLC patients who harbor somatically activated oncogenes such as EGFR and BRAFV600, rearranged ALK or ROS1, or PD-L1 expression ≥50% of tumor cells." (PMID 30818873, 2019). "YAP inhibition suppressed tumor growth in resistant cells, patient‐derived xenograft, and EML4‐ALK transgenic mice, whereas YAP overexpression decreased the responsiveness of parental cells to ALK inhibitor." (PMID 31633304, 2019). "We show here that the TYK2 tyrosine kinase is expressed in human ALCLs irrespective of ALK status and is essential for tumor cell viability." (PMID 30131584, 2019). "And high expression of eIF3E and eIF3J was observed more in patients with residual tumours (13/4 vs. 172/170, p = 0.0456) and without mutations in KRAS/EGFR/ALK (47/48 vs. 86/46, p = 0.0206), respectively." (PMID 31885740, 2019). "An iris biopsy was performed, and immunocytochemistry analysis showed that the tumor cells were positive for cytokeratin (CK)-CAM5.2 and CDX2 and negative for CK7, CK20, thyroid transcription factor 1 (TTF-1), and anaplastic lymphoma kinase (ALK)." (PMID 30841908, 2019). "PD-L1 expression in a tumor sample obtained by bronchoscopy was negative, and the status of ROS1 and ALK rearrangements and EGFR mutation were non-informative." (PMID 30986912, 2019). "FOXM1 was found to be highly expressed in the nuclei of these ALK-expressing tumor cells with the surrounding benign cells being negative." (PMID 31390744, 2019). "Patient CRUK0056 was not a candidate to receive targeted therapies since her tumour was classified as stage IB and she did not harbour any mutation associated to known driver genes (e.g., EGFR, ALK, ROS1, BRAF, RET)." (PMID 31540260, 2019). "In October 2016, FDA has approved pembrolizumab for the first-line treatment of patients with metastatic NSCLC whose tumors have high PD-L1 expression (≥50% PD-L1 expression) with no EGFR or ALK genomic tumor aberrations based on the study of KEYNOTE-024." (PMID 31205619, 2019). "Among all 70 non-BRAF V600E-mutated cases, only one case with ALK fusion (confirmed by positive ALK[D5F3] IHC) provided a false positive result with positive cytoplasmic and nuclear staining in 80% of tumor cells." (PMID 31234388, 2019). "PCR-based methods are not recommended for routine use for ALK rearrangement detection from circulating tumor DNA (ctDNA)." (PMID 31154543, 2019). "In contrast to crizotinib, ceritinib is 20 times more potent as crizotinib for ALK fusion, yet no tumor activity against MET was observed." (PMID 31023335, 2019). "Based on this evidence, platinum-based chemotherapy plus PD-1/PD-L1 inhibitor is strongly recommended in patients with PS 0–1, whose tumor is positive for PD-L1 ≥ 50%, and who do not have EGFR mutation or ALK rearrangement." (PMID 31049758, 2019). "Meanwhile, the N-terminal EML4 protein was expressed in all tumor tissues independent of ALK fusion status." (PMID 30943926, 2019).
tumor (continued). "The assessment of CTCs to determine EGFR mutation status, ALK rearrangements and PD-L1 status lends itself to the identification of patients for targeted therapies, be they oncogenic or immune-related, in patients where tumour biopsy tissue may not be available." (PMID 30889898, 2019). "YAP silencing suppressed tumor growth in resistant cells, patient‐derived xenografts, and EML4‐ALK transgenic mice, whereas YAP overexpression decreased the responsiveness of parental cells to ALK inhibitor." (PMID 31633304, 2019). "When tested against 16 protein kinases involved in the regulation of tumor growth and metastasis, P03F03 inhibited anaplastic lymphoma kinase (ALK), focal adhesion kinase (FAK), insulin like growth factor (IGF11-R), proto-oncogene SRC, and vascular endothelial growth factor (VEGF-R2 R2)." (PMID 31491907, 2019). "Detecting tumor markers such as EGFR, ALK, ROS1, and PDL-1 in the blood or plasma might not only guide management, but also detect early therapy resistance, relapse, and establish a prognosis." (PMID 31818027, 2019). "The comparison of survival of patients with ALK wild-type or ALK mutation, with or without MYCN amplification showed a poorer survival in patients whose tumours harbour MYCN amplification, with or without ALK mutation." (PMID 30778092, 2019). "Although, the majority of tumor samples showed no CNA of ALK, PDGFRA, VEGFR2/KDR, FGFR1, and to a lesser extent of MET in both primary and recurrent samples, the concordance of CNA status varied substantially in the subset of cases with alterations." (PMID 30894200, 2019). "This raises the possibility that NB tumours with 2p gain may instead benefit from extra copies of MYCN and ALK wildtype receptor in collaboration with its recently described ligand, ALKAL2 located at 2p25." (PMID 30778092, 2019). "Immunohistochemistry showed strong positive expression of PD-L1 (> 50% of tumor cells) with no EGFR or ALK genomic tumor aberrations." (PMID 30832704, 2019). "Consistent with this, in 44 ALK+ and ALK− ALCL tumor samples, 82% were SHP-1 negative by immunohistochemistry, and this was frequently as a result of methylation of the SHP-1 promoter." (PMID 31684088, 2019). "The tumor of the palate mucosa was likewise identified as an adenocarcinoma, and the cells showed cytological similarities with the tumor cells in the pleural effusion; TTF-1, Napsin A, EGFR mutation and ALK translocation were all negative." (PMID 30634950, 2019). "The expression of ALK-wt, ALK-F1174L, or ALK-R1275Q in NC progenitors or in sympathetic neuroblasts is not sufficient to drive NB tumor formation in absence of MYCN or other NB prototypical genetic alterations." (PMID 31058082, 2019). "Thus, although scarce, concomitant genetic alterations appear to be another important determinant of tumor biology and patient outcome in ALK-driven NSCLC, beside the oncogenic driver, i.e. the ALK fusion itself." (PMID 31139322, 2019). "Usually the architecture of lymph nodes is partially effaced in ALK+ ALCL; the tumor cells commonly infiltrate the subcapsular sinuses and paracortical region, often showing a striking intrasinusoidal dissemination in a sheet-like pattern, mimicking a metastatic carcinoma." (PMID 29617304, 2018). "Concerning the ALK FISH pattern, two of them displayed SRS in > 60% of the tumor cells." (PMID 30466405, 2018). "Combined inhibition of ALK and BRAF dramatically reduced tumour growth in vivo." (PMID 30290811, 2018). "Five lung ADC tumor cores are shown, including one ALK-positive and four ALK-negative cases, as assessed by IHC." (PMID 30326973, 2018). "This might play an important role in protective tumor immunity as well as in the maintenance of the CTL memory response and the production of antibodies against ALK." (PMID 29642597, 2018).
tumor (continued). "Subsequently, pembrolizumab, another anti-PD-1 antibody, was approved as a second-line for NSCLC patients whose tumors exhibit >50% of PD-L1 expression and as first-line treatment in patients PD-L1 positive, with no EGFR or ALK genomic tumor aberrations." (PMID 29464099, 2018). "The tumor cells were diffusely positive for factor XIIIa and ALK, but were negative for AE1/AE3 keratin, alpha-smooth muscle actin, CD30, CD34, CD68, PU.1, melan A, MITF, and S-100 protein." (PMID 29747676, 2018). "The ICC staining pattern of these 4 cases showed intratumoral heterogeneity and moderate staining intensity, which is not a common phenomenon in ALK IHC based on FFPE tissue in that it often demonstrates diffuse strong tumor tissue staining." (PMID 30572846, 2018). "Indeed, our preclinical data presented here show that combination of the ALK inhibitor crizotinib and the mTOR inhibitor rapamycin results in rapid and robust abrogation of MPM tumor growth in vivo." (PMID 29755689, 2018). "ALK gene rearrangement not only helps in identifying the characteristics of IMT, but also provides the opportunity to perform targeted therapy on this rare but sometimes aggressive tumor." (PMID 29888269, 2018). "Patients with ALK-translocation-positive tumours have significantly longer OS compared to those without any mutations (p = 0.0029) and to those with other and null mutations (p = 0.022)." (PMID 29854298, 2018). "Amongst these tumours, ROS1 rearrangements never overlap with ALK fusions, and rarely co-occurr with oncogenic EGFR mutations (0.5%; 1/220) or KRAS mutations (1.8%; 4/220)." (PMID 29455670, 2018). "In this study, crizotinib as mono-drug did not exert anti-tumor efficacy in an ALK-positive xenograft tumor, but was effective when applied simultaneously with rapamycin." (PMID 29755689, 2018). "Patients with ALK-translocation-positive tumours have significantly longer OS compared to those without any mutations (HR = 0.33; 95% CI: 0.16–0.68; p = 0.0029) and to those with other and null mutations (HR = 0.44; 95% CI: 0.22–0.89; p = 0.022)." (PMID 29854298, 2018). "In the clinical practice, Pembrolizumab is already approved by FDA for first-line treatment of patients with metastatic NSCLC who shows ≥50% PD-L1-positive TCs, with no EGFR or ALK genomic tumor aberrations." (PMID 29467945, 2018). "One study described the case of a 78-year-old male ex-smoker with ALK- rearranged Sq-LC who did not respond to alectinib, although the tumor cells were found to be diffusely and strongly positive for ALK rearrangement by IHC and FISH." (PMID 29844868, 2018). "Compared to the ALK-positive core, no specific ALK signal was detectable in the tumor epithelia of the four negative cases; un-specific signal was detectable in the stromal compartment, like the intra-alveolar macrophages." (PMID 30326973, 2018). "Addition of ALK-inhibitors in ALK-positive NSCLC may therefore augment local control effects of radiotherapy and in parallel provide a systemic therapy option to prevent distant tumor growth as the key pattern of therapy failure." (PMID 29304828, 2018). "One xenograft harboured an ALK fusion as sole driver event, however we lacked the corresponding patient tumour." (PMID 28186126, 2017). "The tumor was tested by immunohistochemistry (IHC) for TRKA, ROS1 and ALK proteins whose expression may indicate the result of a genetic alteration." (PMID 28903424, 2017). "One MECA de novo tumor harbored a fusion between exon 9 of moesin (MSN) and exon 20 of ALK." (PMID 29084941, 2017). "It is worth noting that the tumor with the strongest expression of ALK without expression in GSC corresponded to the patient with the longest overall survival." (PMID 28960893, 2017). "Patients with ALK gene rearrangement had no expression of PD-L1 on tumor cells in IHC assay with 22C3 antibody." (PMID 28969070, 2017).